GSK3B (glycogen synthase kinase 3 beta)
Diseases named in the same sentence as GSK3B in open-access papers (continued):
Sharing a sentence is not in itself a finding about the gene and the disease.
Cognitive impairment (continued). "Conditional overexpression of GSK-3β causes neuronal death, hyperphosphorylation of tau protein and cognitive impairments in mice, while GSK-3β inhibitors have been found to reverse cognitive deficits in several rodent models of AD." (PMID 34706756, 2021). "This study showed that moderate overexpression of GSK3β in the striatum of HD mice attenuates brain atrophy, motor impairment and cognitive deficits." (PMID 34072862, 2021). "Acupuncture therapy was also shown to attenuate the AD-induced cognitive impairments via upregulating the stabilisation of the cellular signal but downregulating GSK-3β or negative regulation of neuroinflammation." (PMID 32337259, 2020). "Treatment with LiCl ameliorated SEV‐induced cognitive disorder in rats by inhibiting the GSK‐3β/β‐catenin signaling pathway." (PMID 31867790, 2020). "This research was aimed to reveal the role of GSK‐3β inhibition on cognitive impairment induced by SEV anesthesia." (PMID 31867790, 2020). "Here we show that increasing GSK-3β activity in adult animals reproduces the first signs of AD, at least about tau protein and cognitive deficit." (PMID 33013321, 2020). "This study demonstrates that GSPs ameliorate neuronal oxidative damage and cognitive impairments in an experimental sporadic AD model by inhibiting GSK-3β-dependent mPTP opening." (PMID 31232699, 2019). "This GSK-3β-induced cognitive impairment is mediated by tau protein because the genetic deletion of tau as well as GSK-3β inhibition blocks Aβ-induced impairments of LTP." (PMID 31191636, 2019). "The main findings of the present study indicate that GSPs ameliorate neuronal oxidative damage and cognitive impairments in AD by inhibiting GSK-3β-dependent mPTP opening." (PMID 31232699, 2019). "In conclusion, GSPs ameliorate neuronal oxidative damage and cognitive impairment by inhibiting GSK-3β-dependent mPTP opening in AD." (PMID 31232699, 2019). "Vanillic acid, known to be abundant in the senses, increased the content of p-Akt and decreased the activity of GSK-3β in mouse models with amyloid beta-induced cognitive impairment." (PMID 29772805, 2018). "Pharmacological treatments, which inhibit GSK-3β, have been reported to repair cognitive impairment in AD mice." (PMID 29891841, 2018). "Pharmacological treatments, which inhibit GSK-3β, have been reported to reduce cognitive impairment in AD mice." (PMID 29891841, 2018). "It has been confirmed the phosphoinositide 3-kinase (PI3K)/AKT/glycogen synthase kinase-3β (GSK-3β) pathway are induced due to isoflurane anesthesia induced-inflammation, stress, and apoptosis, thus resulting to cognitive impairment." (PMID 30349449, 2018). "In the present study, lithium was found to restore cognitive impairment and reduce the phosphorylation of GSK3β by multiple isoflurane exposures." (PMID 27057548, 2016). "Our results indicate that the intracellular kinases Akt and GSk3β play a critical role in the ethanol-induced suppression of γ oscillations and reveal new cellular pathways involved in the ethanol-induced cognitive impairment." (PMID 27582689, 2016). "Recent studies have shown that Akt/GSK3β signaling is also involved in the beneficial effect of curcumin on Aβ-induced cognitive impairments." (PMID 26114940, 2015). "In this regard, we have demonstrated that neuronal GSK-3β overexpression causes a drastic decrease in postsynaptic density number and volume in hippocampal granule neurons, a phenomenon that may be related to cognitive impairment and altered LTP generation previously observed in these mice." (PMID 24904272, 2014). "In this context, Wnt signaling is activated after GSK-3β inhibition by lithium, and this phenomenon protects against cognitive impairment." (PMID 25524173, 2014). "The deletion of tau in GSK-3β-overexpressing mice significantly ameliorates memory impairments, thus indicating that tau phosphorylation contributes to this cognitive impairment." (PMID 24904272, 2014).
Cognitive impairment (continued). "Several studies correlate Aβ-induced cognitive impairments with GSK-3β phosphorylation of tau protein residues resulting in cytoskeletal disorganization, synaptic loss and axonal disruption." (PMID 25187954, 2014). "In contrast, GSK-3β overexpression (both the native and constitutively active forms of the enzyme) leads to cognitive impairment." (PMID 24904272, 2014). "In summary, increased GSK-3β activity has been used to model events occurring in AD, interventions that exacerbate cognitive impairments, and neuropathology in rodent models of AD." (PMID 24904272, 2014). "In this regard, inhibitors of GSK-3β have been reported to rescue cognitive deficits in several murine models of AD." (PMID 24904272, 2014). "The activation of GSK3β has been shown to promote Aβ production and aggregation, leading to excessive Tau protein phosphorylation and subsequent neurofibrillary tangle formation, ultimately resulting in neuronal damage and cognitive deficits." (PMID 40430426, 2025). "Indeed, regulating the Wnt/GSK-3β/β-catenin signaling pathway by ginsenoside alleviate oxidative stress, neuro-inflammation, protect neurons, and improve the cognitive impairment in AD." (PMID 40251348, 2025). "Previous studies have shown that resveratrol can reduce ROS levels by regulating autophagy via the AMPK-mTOR pathway and lithium chloride has been shown to improve cognitive impairments by inhibiting apoptosis and oxidative stress through the GSK-3β/β-catenin signaling pathway." (PMID 41099906, 2025). "Alisol A was shown to lead to neurovascular protection in cerebral ischemic mice through the activation of the AKT/GSK3β signaling pathway; the compound attenuated the neurological deficits and cognitive deficits and inhibited IL-6 and IL-1β expression, in addition to promoting neuronal survival." (PMID 40070574, 2025). "Thus, GSK3β has been considered as a promising therapeutic target for treating AD and mitigating cognitive impairment." (PMID 39996845, 2025). "PP2A and GSK3β play an important role in regulating phosphorylated tau and cognitive impairments." (PMID 40426884, 2025). "Furthermore, SHE administration can ameliorate cognitive impairment caused by SCO by enhancing neuron survival and synaptic plasticity through the activation of the ERK/CREB/BDNF and PI3K/Akt/GSK-3β signaling pathways in mouse hippocampus." (PMID 40949138, 2025). "The necessity to verify the accuracy, sensitivity, and specificity of platelet GSK-3β activation as a predictive biomarker for cognitive impairment, as well as its potential application in a broader range of diseases, needs to be verifying in more large-scale, longitudinal studies." (PMID 38660514, 2024). "Schisandrin B can attenuate Aβ‐induced cellular damage and cognitive impairment in AD mice and may act as a potential selective ATP‐competitive GSK‐3β inhibitor, further affecting its anti‐AD effect." (PMID 39129397, 2024). "Recent research indicates that overactivation of GSK-3β could impair the developing hippocampus and contribute to cognitive deficits." (PMID 38536552, 2024). "In addition, GSK3β activity in the platelets is augmented and correlated with cognitive impairment and disease severity in AD patients." (PMID 39644152, 2024). "Therefore, a well-established model integrating aging, ApoE ε4 genotype and elevated platelet GSK-3β activities has great potential to predict the development of cognitive impairment in patients with T2DM." (PMID 38660514, 2024). "The underlying mechanism behind this GMB transmission-associated cognitive impairment may involve butyric acid, a short-chain fatty acid produced by GMB, which impacts acetylation-regulated phosphorylation in GSK3β." (PMID 37162940, 2023). "Preclinical evidence has shown that intranasal insulin may also ameliorate cognitive deficits in 6-hydroxylase dopamine (6-OHDA)-induced rat models of PD by regulating the Akt/Glycogen Synthase Kinase 3 Beta (GSK3β) signaling pathway." (PMID 37893474, 2023).
Cognitive impairment (continued). "To determine the structural basis underlying the therapeutic effects of GSK3β inhibition on adolescent METH exposure-induced behavioral and cognitive deficits in adulthood, we examined the synaptic ultrastructure in the DHP CA1 subregion using transmission electron microscopy." (PMID 36949769, 2023). "Hyperactive GSK3β in the Cornu Ammonis 1 (CA1) subregion of the dorsal hippocampus (DHP) was associated with adolescent methamphetamine (METH) exposure-induced behavioral and cognitive deficits in adulthood." (PMID 36949769, 2023). "GSK‐3β activation acts as a mediator between ApoE ε4 and cognitive impairment." (PMID 37700547, 2023). "Restoration of Akt/GSK-3β pathway by GP might correct AD-like pathological changes and ameliorate cognitive deficits." (PMID 38095632, 2023). "Alisol A could exert an important role in neurovascular protection and alleviate cognitive impairment through activation of the AKT/GSK3β pathway in CI mice." (PMID 37889534, 2023). "Inhibition of miR-129 by miR-129 antagomir could attenuate NLRP3/caspase-1 mediated pyroptosis and improve cognitive impairment by activating IGF-1/GSK3β signaling pathway via directly targeting IGF-1." (PMID 37332874, 2023). "For drug addicts, hyperphosphorylated tau positive (AT8, AT100) nerve fibers were significantly increased in the frontal and temporal cortex and locus coeruleus, and GSK-3β increased, showing brain lesions related to early AD patients, leading to cognitive impairment." (PMID 36937655, 2023). "Furthermore, activation of GSK-3β has been shown to induce Tau hyperphosphorylation and cognitive impairment." (PMID 36844418, 2023). "Given that the GSK‐3β activity can be regulated by ApoE in vitro, we hypothesize that the activation of GSK‐3β may play a mediative role between ApoE ε4 and cognitive impairment in T2DM patients." (PMID 37700547, 2023). "Taken together, these data provide further understanding into the regulation of CBS and in particular into the genetic relationship between DYRK1A and CBS through the Akt/GSK3β and NF-κB pathways, which should help develop more effective therapies to reduce cognitive deficits in people with DS." (PMID 36711154, 2022). "Pathologic activation of GSK3β signaling leads to neurodegenerative/neuropsychiatric diseases, but its involvement in oxidative stress-induced neurodevelopmental disorders and cognitive deficits is uncharacterized." (PMID 35589394, 2022). "KEGG enrichment analysis indicated that the PI3K/Akt/GSK3β/Nrf2 /HO-1pathway may be involved in the regulation of cognitive impairment by ASF." (PMID 35794585, 2022). "A previous study also revealed that increased NGF and TrkA expression and activation of the Akt/GSK3β pathway could ameliorate brain hypoperfusion-induced cognitive impairment in rats." (PMID 35565989, 2022). "Our results indicate that cognitive impairment resulting from oxidative damage may be alleviated through attenuation of aberrant GSK3β activity." (PMID 35589394, 2022). "Although valproate effects on GSK-3β may explain cognitive impairment, further neurotoxicological studies are needed to confirm an underlying mechanism and to close the argument that valproate exerts varying cognitive effects in different studies." (PMID 35966480, 2022). "However, the results of a different study, indicated that blockade of GSK-3β by siRNA diminished cognitive impairments in the Fmr1–/– mice." (PMID 35126052, 2021). "LiCl improved the SEV‐induced cognitive impairment by inhibiting apoptosis and oxidative stress through suppression of the GSK‐3β/β‐catenin signaling pathway, and LiCl could become a therapeutic agent in treating SEV anesthesia‐induced neurodegeneration." (PMID 31867790, 2020). "Furthermore, the increase in GSK-3β expression in the adult animals triggered a cognitive deficit, as determined through the hippocampus-dependent object recognition test (OR)." (PMID 33013321, 2020).
Cognitive impairment (continued). "A recent study showed that GSK-3β activity is upregulated in cognitively impaired T2DM patients, in comparison with DM patients with no cognitive impairment, thus confirming the association between GSK-3β peripheral activity and cognitive impairment in T2DM." (PMID 32872672, 2020). "Moreover, it was proven recently that amla, a major constituent of Antia, exerted a significant modulation of the p-AKT/GSK-3β pathway, resulting in a decline of phosphorylated tau and amelioration of cognitive deficits." (PMID 32655767, 2020). "The reduction in the inhibitory phosphorylation of Gsk3β aggravates cognitive impairment." (PMID 30838024, 2019). "Taken together, we can assume that p-GSK-3β may mediate neuronal protection of GSPs by inhibiting neuronal oxidative damage, mitochondrial dysfunction and cognitive impairments." (PMID 31232699, 2019). "Increased expression of GSK-3β, Tau, and other substrates may be involved in AD symptoms, including cognitive deficits." (PMID 31467920, 2019). "Once the Akt is activated by AM404, the activated Akt (pS473Akt) could phosphorylate GSK3β (at S9 site, and become an inactive form), which could further reduce the features of AD, including Aβ, tau, inflammation, and cognitive impairment." (PMID 30426182, 2019). "We speculated that ISL may protect against LPS-induced cognitive impairment by suppressing oxidative stress and inflammation in the hippocampus, and that GSK-3β and NRF2 signaling pathways participate in the therapeutic effects of ISL." (PMID 31387531, 2019). "Accordingly, lithium and specific GSK-3β inhibitors ameliorate cognitive deficits induced by CMS." (PMID 31191636, 2019). "In this context, the increase of GSK-3β and tau expression may be involved in AD symptoms, including cognitive deficits." (PMID 31467920, 2019). "In conclusion, insulin and IGF-1 may alleviate cognitive impairment in PD via the inactivation of GSK3β mediated by PI3K/Akt." (PMID 29515352, 2018). "The overexpression of GSK3β in cortex and hippocampus results in signs of neurodegeneration and spatial learning deficits in in vivo models, whereas its inhibition results in improvements in cognitive impairment in these rodents." (PMID 29515352, 2018). "This evidence suggests that GSK-3β is not only the major player in Tau pathology, but may also be responsible for the cognitive impairments seen in SAMP8 mice." (PMID 29346315, 2018). "The genetic overexpression of GSK3β in cortex and hippocampus results in signs of neurodegeneration and spatial learning deficits in in vivo models, whereas its inhibition results in improvements in cognitive impairment in these rodents, including AD and PD." (PMID 29515352, 2018). "Hyperactive GSK3β is conjectured to be neuropathological; therefore inhibiting its activity may offer as a promising therapeutic option for treating cognitive impairments." (PMID 29449801, 2018). "Because the PI3K/Akt signaling pathway is activated by BDNF, our results suggested that SM70EE inhibits phosphorylation of GSK-3β by activating the BDNF/PI3K/Akt signaling pathway in mouse hippocampus to ameliorate the cognitive impairment induced by the I.C.V. injection of Aβ1–42." (PMID 29137190, 2017). "Lithium prevented GSK3β overactivation and alleviated isoflurane-induced cognitive deficits." (PMID 27057548, 2016). "We demonstrate an association between a persistent neuronal DDR, increased cholesterol biosynthesis, impaired insulin/IGF and Wnt signalling, and increased GSK3β, which may contribute to neuronal dysfunction and cognitive impairment." (PMID 26095650, 2016). "However, DFO alleviated the reduction by phosphorylating GSK3β in the hippocampus and regulated GSK-3β activity in response to LPS, thus providing protection from LPS-induced apoptosis and cognitive impairment." (PMID 25644393, 2015).
Cognitive impairment (continued). "In view of this evidence and previous studies showing that GSK3β activation is involved in the mechanisms of HIV neurotoxicity, we concluded that targeting the GSK3β pathway with lithium might be of value in the management of the cognitive impairment." (PMID 19399237, 2009). "Notably, there was also a study showing that mild inhibition of mitochondrial complex I activates AMPK and inhibits GSK3β activity, which could reduce Aβ and tau phosphorylation, restore axonal transport and prevent cognitive deficits in 5× FAD mice." (PMID 40926280, 2025). "Furthermore, our meticulous dissection of this phenomenon uncovers the intricate orchestration through the PI3K/AKT/Gsk3b signaling pathway, ultimately giving rise to an augmented phosphorylation of tau protein and the ensuing manifestation of cognitive impairment." (PMID 38493090, 2024). "Furthermore, inhibition of AKT/GSK3β was involved in ischemia-induced cognitive impairment." (PMID 37889534, 2023). "However, the relationship between ApoE ε4 and GSK‐3β in the cognitive impairment of T2DM patients remains unclear." (PMID 37700547, 2023). "Cognitive impairment in transgenic AD models is also accompanied by accumulations of phosphorylated tau, which are composed of aberrant forms of phosphorylated tau; indeed, higher activities of GSK3β and Cdk5 kinases result in accumulation of hyperphosphorylated tau in 12-month-old APPswe mice." (PMID 35408893, 2022). "In conclusion, we found in the current study that GSK-3β activation in the NSCs of mice with accelerated senescence expedited the consumption of AHN pool, resulting in a transient increase but induced long-term AHN deficits and associated cognitive impairments." (PMID 32863953, 2020). "Thus, we speculated that LiCl suppressed the GSK‐3β activation, which resulted in reduced neuron apoptosis and oxidative stress, ultimately contributing to improvement of cognitive deficits." (PMID 31867790, 2020). "Although previous studies have confirmed that GSK-3β inhibition may be an effective strategy to improve cognitive impairment in schizophrenic patients, it should be noted that all antipsychotic drugs currently used clinically are antagonists against D2 receptors." (PMID 32143671, 2020). "Moreover, the potentially distinct functions of GSK-3β and Nrf2 in cognitive disorders have not been linked to their possible combinatorial roles." (PMID 30079246, 2018). "It suggested that SCE could improve the depression-like emotional status and associated cognitive deficits in CUMS mice, which might be mediated by regulation of BDNF levels in hippocampus, as well as up-regulating of TrkB/CREB/ERK and PI3K/AKT/GSK-3β pathways." (PMID 28761074, 2017). "The protective effects of APAP on cognitive impairment in mice may be related to its antioxidant and anti-inflammatory activity, modulating the activity of GSK3β, as well as its ability to inhibit the mitochondrial permeability transition (MPT) pore and the subsequent apoptotic pathway." (PMID 28109286, 2017). "Furthermore, scientists have also proved that inhibition of AKT could result the increased activity of GSK3β correlated with higher expression of tau S396 and cognitive impairment." (PMID 27965573, 2016). "To further evaluate the potential of GSK‐3β as a therapeutic target for AD‐like pathologies and cognitive impairments in ApoE4‐T2DM conditions, we administered intraperitoneally 9‐ING‐41, a specific small‐molecule inhibitor of GSK‐3β, into the ApoE4‐T2DM mice." (PMID 40905109, 2025). "The GSK3β inhibitors TFGF-18 and ISO modulate the gut homeostasis and barrier function to inhibit neuroinflammation and attenuate cognitive impairment by regulating NF-κB, and Nrf2/HO-1 pathways." (PMID 40741047, 2025). "Overall, these data suggest that inhibiting GSK‐3β by 9‐ING‐41 effectively mitigates synaptic deficits and cognitive impairment in ApoE4‐T2DM mice." (PMID 40905109, 2025).